CXCR3 (C-X-C motif chemokine receptor 3)
Diseases named in the same sentence as CXCR3 in open-access papers (continued):
Sharing a sentence is not in itself a finding about the gene and the disease.
thyroiditis (4 papers, 2016 to 2024). Inflammation of the thyroid gland. "A significant increase of CXCR3B expression was found in thyroiditis compared to B-CLT (0.5747±0.433, p=0.0199), while both CXCR3 variants showed a statistical increment in nMPTC tumors compared to thyroiditis (CXCR3A: 1.593±0.7143, p=0.0171; CXCR3B: 1.240±0.5445 p=0.0004)." (PMID 29416784, 2018). "To determine if changes in the CXCR3 expression profile are indeed associated to thyroid chronic inflammation, we analyzed the protein profile of CXCR3A and CXCR3B in tissues with thyroiditis and compared them to B-CLT, benign and nMPTC tumors." (PMID 29416784, 2018). "Since IFN-γ induces the secretion of CXCR3 ligands and CXCL10 in normal and PTC thyrocytes, it has been proposed that CXCR3 chemokines may promote thyroid malignant transformation and/or thyroid cancer progression." (PMID 29416784, 2018). "Our findings prompted us to analyze the expression profile of CXCR3 in a papillary thyroid cancer cell line (TPC-1) as well as in benign and malignant thyroid neoplasms to determine if expression profiles are associated to thyroid malignant phenotypes." (PMID 29416784, 2018). "Thyroiditis was found in 30% of PTC specimens and all cases with chronic inflammation showed a high frequency for CXCR3 reactive cells." (PMID 29416784, 2018). "Studies on RAETL1 in thyroid cells demonstrated that anaplastic cancer cell lines are sensitive to NK cell-mediated lysis via ULBP2/5/6 and chemoattractant CXCR3-positive NK cells, suggesting that patients with ATC may benefit from NK cell-based immunotherapy." (PMID 38610938, 2024). "Most of our PTC specimens with high CXCR3 staining were cases without thyroiditis and no major differences in CXCR3 immunoreactivity were found between PTC with or without thyroiditis." (PMID 29416784, 2018). "We could show that the expression of chemokine receptors CXCR3, CCR5, and CRTH2 is upregulated in thyroid-infiltrating lymphocytes from thyroid nodules as compared to lymphocytes from peripheral blood." (PMID 27872865, 2016). "In addition, CXCR3A and CXCR3B protein levels in nMPTC were higher in patients without thyroiditis supporting that increased expression of CXCR3 is predominantly from epithelial cancer cells." (PMID 29416784, 2018). "Moreover, PTC-CLT with or without thyroiditis, showed similar CXCR3 intensity levels." (PMID 29416784, 2018).
triple-negative breast carcinoma (4 papers, 2021 to 2026). An invasive breast carcinoma which is negative for expression of estrogen receptor (ER), progesterone receptor (PR), and human epidermal growth factor receptor 2 (HER2). "Here, we identify the interferon-inducible chemokine CXCL10 and its receptor CXCR3 as key regulators of immunological dormancy in triple-negative breast cancer (TNBC)." (PMID 41617729, 2026). "The results indicate that triple-negative breast cancer samples show transcriptomic profiles consistent with increased lymphocyte infiltration compared to other subtypes and identify CXCR3 as a potential mediator of that increased recruitment." (PMID 34440489, 2021). "Cytokines, which could mediate this exercise-dependent effect on triple-negative breast cancer cell growth, were identified, and we focused on the CXCR3 axis in further experiments." (PMID 40362215, 2025). "CXCL9 is a ligand for CXCR3, and both CD8+ T-cell infiltration and the therapeutic efficacy of dual PD-1/CTLA-4 blockade were shown to be CXCR3 dependent using a mouse model of triple-negative breast cancer." (PMID 38261139, 2024). "Analysis of CXCR3 expression across the molecular subtypes revealed increased CXCR3 expression in HER2-enriched and triple-negative breast cancer subtypes, compared to the luminal subtypes." (PMID 34440489, 2021).
uveitis (4 papers, 2014 to 2020). An inflammatory process affecting a part of or the entire uvea. "This correlated with reduced expression of CXCR3 and α4 integrin, suggesting that p35 might also mitigate uveitis by suppressing trafficking of inflammatory cells into the retina during EAU." (PMID 28959012, 2017). "Because CXCR3 is considered a marker of the main producers of IFN-γ in the T cell population, CXCR3+ T cells may be the primary effectors of the maintenance of uveitis in BD." (PMID 25061613, 2014).
allergic rhinitis (3 papers, 2006 to 2024). Inflammation of the nasal mucous membranes caused by an IgE-mediated response to external allergens. "Notably, CXCR3 expression in T cells is reduced in allergic rhinitis patients at the onset of the disease." (PMID 39399526, 2024).
apical periodontitis (3 papers, 2021 to 2024). "Application of a CXCR3 antagonist inhibited inflammatory cell migration leading to reduced lesion size of the apical periodontitis, clearly implying a crucial role for the CXCL9-CXCR3 cascade in early inflammation." (PMID 35794867, 2022).
Arthralgia (3 papers, 2016 to 2022). "However, CXCR3 expression in LNs was associated with arthralgia and pericarditis in patients with AOSD, suggesting that the chemokine was associated with these conditions." (PMID 31101882, 2019).
atopic dermatitis (3 papers, 2006 to 2023). "Thus, we propose that neutrophils promote chronic itch in atopic dermatitis via upregulation of CXCL10 and subsequent activation of CXCR3-dependent itch pathways." (PMID 31631836, 2019).
celiac disease (3 papers, 2014 to 2025). An autoimmune genetic disorder with an unknown pattern of inheritance that primarily affects the digestive tract. "Today, the importance of the expression of genes CCR5 and CXCR3 in the pathogenesis of celiac disease is well known." (PMID 38040898, 2023). "Especially, the gluten-specific CD4+ T cells are known to express CXCR3, responding to the CXCL9 and CXCL10 that are expressed in the coeliac regions, for which CXCL9 and CXCR are suggested as the therapeutic targets for the coeliac disease." (PMID 39897058, 2025).
chlamydial infection (3 papers, 2017 to 2020). "In order to access how CXCR3 deficiency affects dendritic cells function in the event of chlamydial infection, we infected CXCR3−/− and WT mice intravaginally." (PMID 29552679, 2017). "Although CXCR3 and its ligands are crucial for Th1 cells activation and migration, much of CXCR3’s role in chlamydial infection pathogenesis remains unexplored." (PMID 29552679, 2017). "This demonstrates that the CXCR3−/− mice can effectively resolve chlamydial infections, even though they possess a higher bacterial burden during infection course." (PMID 29552679, 2017). "Taking together, our research demonstrates that chemokine receptor CXCR3 involves a variety of immune cells activation and trafficking in chlamydial infection mouse model." (PMID 29552679, 2017). "Our results highlight the diverse roles of CXCR3 in chlamydial infection: it regulates and enhances host defense mechanisms against infection, and also contributes to tissue inflammation and pathology." (PMID 29552679, 2017). "CXCL11 can induce and recruit CXCR3+ T cells shown to be protective during chlamydial infection, and could therefore prevent ascension." (PMID 32127796, 2020). "In summary, this first report reveals that CXCR3 not only regulates Th1 T cell activation and trafficking, but also modulates CD8+TNF-a+, cDC, pDC, neutrophil and NK cells in chlamydial infection." (PMID 29552679, 2017). "Together, our study suggests CXCR3 regulate CD8, CD8+TNF-a+ and neutrophils, those cells are involved or partially involved in inducing tissue pathology following chlamydial infection." (PMID 29552679, 2017).
cholestasis (3 papers, 2011 to 2018). Impairment of the bile flow caused by obstruction within the liver, or outside the liver in the bile duct system. "Under cholestasis the expression of a specific chemokine subset in the liver is reduced mainly affecting the CCR2 and CXCR3 axes of immune cell trafficking." (PMID 29953538, 2018). "Cholestasis in the BDL model severely impaired pathogen-induced chemokine expression in the liver affecting CCR2- and CXCR3-dependent cell trafficking." (PMID 29953538, 2018). "In line with our hypothesis, that cholestasis could lead to a higher DPPIV serum activity and therefore higher antagonist form of IP-10 (cIP-10), three HCV patients with increased serum BA showed a trend toward higher frequency of CD3+CXCR3+ T cells in peripheral blood." (PMID 30507970, 2018).
Chronic colitis (3 papers, 2011 to 2020). A chronic inflammatory disease of the large intestine (colon, cecum and rectum). "In the present study, we noted reduced numbers of CXCR3+ T cells in the spleen, MLN and LP after TCDD treatment, which may result from direct inhibition of such cells or indirectly through induction of Tregs, which may result in the amelioration of chronic colitis." (PMID 21858153, 2011).
dermatomyositis (3 papers, 2014 to 2025). Dermatomyositis (DM) is a type of idiopathic inflammatory myopathy characterized by evocative skin lesions and symmetrical proximal muscle weakness. "Both are upregulated in lesional skin of JDM patients and their receptor, CXCR3, is overexpressed in perifascicular infiltrates of dermatomyositis muscle, implicating a role in recruiting IFN-producing plasmacytoid dendritic cells to tissue." (PMID 41488665, 2025). "Strong CXCR3 expression has also been observed in the majority of T cells in both polymyositis and dermatomyositis." (PMID 24939012, 2014). "CXCL10 expression on T cells in the perimysial infiltrates of dermatomyositis and CXCR3 expression on the majority of T cells in dermatomyositis were also reported." (PMID 24939012, 2014). "Juvenile-type dermatomyositis also showed high expression of CXCL10 in muscle tissue and the expression of CXCL10 and recruitment of CXCR3+ T cells were detected in the skin lesions of dermatomyositis." (PMID 24939012, 2014). "In support of this, interferon gamma and tumor necrosis factor alpha, which are increased in IIM, can induce secretion of the CXCR3 ligand CXCL10 by muscle fibers, and CXCR3+ T cells have been identified in the muscle biopsies of polymyositis, dermatomyositis, and inclusion body myositis patients." (PMID 35371068, 2022). "In addition to polymyositis, the CXCL10/CXCR3 axis was also reported to be involved in inclusion body myositis and dermatomyositis." (PMID 24939012, 2014).
dry eye (3 papers, 2013 to 2022). "Ocular acid burns can cause dry eye, and the expression of CXCR3 and CCR5 protein in tears may be related to the occurrence of dry eye after ocular acid burn." (PMID 36522768, 2022). "In this study, the regularity of dry eye manifestations after acid burn and its relationship with CXCR3 and CCR5 were studied, providing clinical reference for the diagnosis and treatment of dry eye after acid burn." (PMID 36522768, 2022). "Similar to the previous reports, in this study, chemokine receptors CCR5 and CXCR3 were found expressed in the tears of patients with dry eye." (PMID 36522768, 2022). "Lymphocyte migration and phagocytosis are key mechanisms of immune inflammatory response, which is considered to be one of the important pathogenesis of dry eye, and CXCR3 and CCR5 play an important role in it." (PMID 36522768, 2022). "In this study, CXCR3 and CCR5 in tears of patients with ocular acid burn were found to be closely related to the manifestations of dry eye, indicating that CXCR3 and CCR5 are involved in the occurrence of dry eye after ocular acid burn." (PMID 36522768, 2022). "We have previously found that desiccating stress stimulates the expression of inflammatory cytokines and Th-1 chemokines and their receptors, CCR5 and CXCR3, in the tear film and ocular surface of an experimental dry eye model." (PMID 27517861, 2016). "In addition, dry eye after ocular acid burn is closely related to the expression of chemokine receptors CXCR3 and CCR5 in tears." (PMID 36522768, 2022). "Secondly, when the chemokine receptor CXCR3 (along with CCR5) expressed by Th1 cells binds to their specific ligands, such as INF-γ, they act as a central mediator to coordinate the localization of CD4+ T cells to the ocular surface to perform an immune response, causing dry eye occurrence." (PMID 36522768, 2022). "Therefore, it may be of clinical significance to investigate the relationship between dry eye and expression of CXCR3 and CCR5 after ocular acid burn." (PMID 36522768, 2022). "Firstly, the extracellular ligand IL-6 directs T cell recruitment by regulating local chemokine secretion and chemokine receptor (CCR4, CCR5, CXCR3, etc.)expression on the CD3+ infiltrate, thus leading to the occurrence of dry eye." (PMID 36522768, 2022). "Current evidence suggests that CXCR3 and CCR5 are potential therapeutic targets for dry eyes." (PMID 36522768, 2022). "CXCR3 and CCR5 may be potential targets for the prevention and treatment of dry eye after ocular acid burn." (PMID 36522768, 2022). "However, further studies to investigate the mechanisms and functions of CXCR3 and CCR5 in dry eye after ocular acid burn are needed to explore better treatment." (PMID 36522768, 2022). "Increased production of CXCR3 and CXCL-9, -10, and -11 have been observed in the ocular surface and increased frequency of CXCR3+ and CCR5+ T cells has been detected in draining lymph nodes of mice with experimental dry eye induced by subjecting them to desiccating stress (DS)." (PMID 24223818, 2013). "Therefore, it deserves further exploration to reveal whether the regulation of CXCR3 and CCR5 pathways to control the immune inflammatory response can be used for the prevention and treatment of dry eye after ocular acid burn." (PMID 36522768, 2022). "However, how CCR5 and CXCR3 play a role in the development of dry eye after ocular chemical burn and whether the content changes of CXCR3 and CCR5 in tears related to the disease progression of dry eye requires further studies." (PMID 36522768, 2022).
encephalomyelitis (3 papers, 2013 to 2016). Inflammation of the brain and the spinal cord. "Previous studies have indicated that CXCR3 mediates CNS accumulation of antibody secreting cells during neurotropic coronavirus-induced encephalomyelitis." (PMID 27242764, 2016). "Intriguingly, a study on a neurotropic coronavirus-induced encephalomyelitis model showed that CXCR3-expressing PBs would infiltrate the CNS and locally produce antibodies against the pathogen." (PMID 24340077, 2013). "Additionally, within the CNS, CXCR3-dependent plasma blast migration into the murine spinal cord during neurotropic coronavirus-induced encephalomyelitis has also been reported." (PMID 27207308, 2016).
endometriosis (3 papers, 2017 to 2025). The growth of functional endometrial tissue in anatomic sites outside the uterine body. "Studies have found that changes in the expression level of CXCR3 are closely related to endometriosis and endometrial cancer and provide help for the differential diagnosis of endometrial cancer." (PMID 34124265, 2021).
epilepsy (3 papers, 2024 to 2025). A brain disorder characterized by episodes of abnormally increased neuronal discharge resulting in transient episodes of sensory or motor neurological dysfunction, or psychic dysfunction. "Studies have shown that A1 astrocyte promoted neuronal ferroptosis via C‐X‐C motif ligand 10/chemokine (C‐X‐C motif) receptors 3 (CXCL10/CXCR3) axis in epilepsy." (PMID 39801259, 2025). "Relatively few studies have examined the relationship between CXCL11/CXCR3 and epilepsy." (PMID 39315097, 2024). "These suggest that CXCL11/CXCR3 may be involved in seizure and provide a rationale for targeting the down-regulation of the CXCL11/CXCR3 axis for the treatment of epilepsy." (PMID 39315097, 2024).
immune deficiency (3 papers, 2013 to 2025). "A positive correlation between CD21lo B cells and CXCR3+ TFH1 cells has been noted previously in CVID patients, suggestive of a mechanism underlying immune dysregulation including the production of autoAbs and immune deficiency in these patients." (PMID 39836489, 2025). "In order to confirm that the phenotype observed in CCR6KO and CXCR3KO mice was specifically due to ablation of CCR6 and CXCR3 in T cells (not a general immune deficiency), CD4+ T cells from CCR6KO or CXCR3KO mice after DS were adoptively transferred to T cell-deficient RAG1KO mice." (PMID 24223818, 2013).
interstitial lung disease (3 papers, 2012 to 2023). A diverse group of lung diseases that affect the lung parenchyma. "For instance, higher levels of CXCR3 and CXCR4 Abs have been observed in the sera of SSc patients compared to the healthy controls, where higher levels of CXCR3 in patients with interstitial lung disease correlate with worse lung function." (PMID 37359516, 2023). "Among the immune cells found in murine models of ILDs, CXCR3+ T-cells in particular are found in inflamed lung tissue or murine models of interstitial lung disease." (PMID 23056449, 2012). "Moreover, the presence of Abs against CXCR3 and CXCR4 in SSc patients indicates a link between autoimmunity and interstitial lung disease, in which both Abs strongly correlate with each other and their concentrations can discriminate patients with stable or decreasing lung function." (PMID 37359516, 2023).
ischemia (3 papers, 2014 to 2024). A hypoperfusion of the BLOOD through an organ or tissue caused by a PATHOLOGIC CONSTRICTION or obstruction of its BLOOD VESSELS, or an absence of BLOOD CIRCULATION. "Both CXCR3 and CXCL10 deficiencies resulted in decreased perfusion recovery in a murine hindlimb ischemia model." (PMID 24868552, 2014). "In conclusion, these results indicate that ER stress-medicated activation of CXCL10/CXCR3 pathway has an important role in retinal inflammation and neuronal injury after high IOP-induced ischemia." (PMID 26448323, 2015).
latent infection (3 papers, 2011 to 2021). "Thus, IP-10 promotes HIV latent infection of resting memory CD4+ T cells through binding with CXCR3." (PMID 34447368, 2021). "Both anti-IP-10 mAb (AD8: P=0.016; NL4-3: P=0.031) and CXCR3 antagonist (AD8: P=0.031; NL4-3: P=0.031) abrogated the IP-10-mediated enhancement of HIV latent infection." (PMID 34447368, 2021). "HSV-1-infected mice were treated with TAK-779 to block CCR5- and CXCR3-mediated CD8+ T cell migration during both acute and latent infections." (PMID 21429183, 2011). "Furthermore, herpes simplex virus promotes CXCR3-mediated migration of CD4+ T cells to sites of infection and CD8+ T cells to sites of latent infection." (PMID 33912186, 2021).
malignant glioma (3 papers, 2020 to 2022). A grade III or grade IV glioma arising from the central nervous system. "This is the first study showing that the suppression of the CCL2/CCR2 and CXCL10/CXCR3 axes by celecoxib may attribute to antitumor effects in a mouse malignant glioma model, in addition to intrinsic and extrinsic apoptotic induction by celecoxib in GSCs." (PMID 32943658, 2020). "Based on these findings, we hypothesized that in GSCs and a GSC-bearing malignant glioma model, modulation of the CCL2/CCR2 and CXCL10/CXCR3 axes by celecoxib might contribute to antitumor effects." (PMID 32943658, 2020).
myositis (3 papers, 2020 to 2025). "Furthermore, we found that the TH1/TC1 markers CXCR3 and CCR5 were differentially overexpressed in IBM, with higher median expression than in any other myositis group." (PMID 40034760, 2025).